Y_RNA (Y RNA )
Gene: Miscellaneous RNA gene on chromosome 15 (44,697,333 to 44,697,430, reverse strand). Ensembl gene ENSG00000206957.
Homologues: Orthologues: chimpanzee Y_RNA (100% identical), macaque Y_RNA (97% identical), pig Y_RNA (74% identical). Paralogues in human: Y_RNA (88% identical), Y_RNA (87% identical), RNY3 (86% identical), Y_RNA (86% identical), Y_RNA (85% identical), RNY3P16 (84% identical), Y_RNA (84% identical), RNY3P1 (83% identical), Y_RNA (83% identical), RNY3P9 (82% identical), Y_RNA (82% identical), RNY3P2 (81% identical), and 94 more.